SP1 (Sp1 transcription factor)
Diseases named in the same sentence as SP1 in open-access papers (continued):
Sharing a sentence is not in itself a finding about the gene and the disease.
prostate carcinoma (continued). "Analyses of the promoter regions of 11 genes expressed in prostate cancer epithelial cells showed that WT1 TFBS overlapped SP1 and EGR1 TFBS, either separately or together." (PMID 18631392, 2008). "Moreover, in various tumors such as prostate cancer, non-small cell lung cancer, and cervical cancer, SP1 is considered to play a significant regulatory role." (PMID 41372957, 2025). "The androgen-responsiveness of the p21 promoter in prostate cancer cells is also due to AR/Sp1 interaction, whereas the induction of the AR coactivator, nuclear receptor interaction protein (NRIP), involves AR-Sp, which includes an androgen response element (ARE) and GC-rich sites." (PMID 39858066, 2025). "This study investigated whether and how Sp1 plays a crucial role in the process of VM in human prostate cancer (PCa) cell lines, PC-3 and DU145." (PMID 35163245, 2022). "Similarly, ZBTB4 can transcriptionally inhibit specific protein transcription factors (Sp1, Sp3, and Sp4), thereby inhibiting the proliferation of prostate cancer cells and promoting cell apoptosis." (PMID 34047477, 2021). "A similar interplay of SP1 and Wnt signal is also observed in prostate cancer." (PMID 34257529, 2021). "One study stated the overexpression of FABP5 in prostate cancer cells can be attributed to hypomethylation of the CpG island in its promoter region, along with up-regulation of the direct trans-acting factors Sp1 (specificity protein 1) and c-Myc." (PMID 32579175, 2020). "Homo sapiens lactate dehydrogenase c (hLdhc) was reported to be expressed in a wide spectrum of tumors, including prostate cancers, and this expression was shown to be regulated by transcription factor Sp1 and CREB as well as promoter CpG island (CGI) methylation." (PMID 29344347, 2018). "In addition, the ETS-related gene (ERG), a member of the E-26 transformation-specific (ETS) family of TFs, is a key factor in prostate cancer, and the SP1 factor is a good target for anti-cancer proliferation." (PMID 29703163, 2018). "This indicates that the connection between ERG, SP1 and prostate cancer could have been identified many years ago." (PMID 29342271, 2018). "A functional Sp1 binding element has been correlated with low HYAL1 expression in bladder and prostate cancer cells, suggesting that Sp1 might impair the promoter activity of HYAL1." (PMID 27764788, 2016). "Although androgen can modulate VEGF expression through Sp1/Sp3 binding site on VEGF promoter in androgen-dependent prostate cancer cells, this route, disappeared as the cells gradually lost their androgen dependency; was replaced by the FABP5-PPARγ-VEGF signalling pathway." (PMID 26814431, 2016). "Ectopic expression of Sp1 or p65 transactivated c-FLIP in all three prostate cancer cell lines." (PMID 25816367, 2015). "Furthermore, Akt is associated with Sp1 phosphorylation in glioblastoma cells and prostate cancer cells, where Sp1 is involved in Akt-mediated induction of VEGF expression that contributes to the growth of tumors by increasing angiogenesis." (PMID 26687764, 2015). "Last but not least, we successfully found an interesting transcription factor Sp1 which could be regarded as a potential novel biomarker for prostate cancer." (PMID 25080090, 2014). "Regulation of VEGF by zinc finger transcription factors, such as Sp1, and the importance of their interactions with AR, suggests that they may play a positive role in promoting angiogenesis and prostate cancer progression." (PMID 23369005, 2013). "In this study we assessed the expression of the anti-apoptotic protein FLIP and its transcription regulators Sp1 and Sp3 by immunohistochemical evaluation of tissue samples obtained from 64 patients who underwent radical prostatectomy as primary treatment for prostate cancer." (PMID 23028678, 2012).
prostate carcinoma (continued). "In this study we assessed the expression of the anti-apoptotic protein FLIP and the transcription factors Sp1 and Sp3 by immunohistochemical evaluation of tissue samples obtained from 64 patients who underwent radical prostatectomy as primary treatment for prostate cancer." (PMID 23028678, 2012). "Increased levels of Sp1/Sp3/FLIP might be related to apoptotic resistance and progression to biochemical recurrence or progression from low- to high-risk prostate cancer." (PMID 23028678, 2012). "However, it has also been proposed that betulinic acid kills prostate cancer cells via activation of selective proteasome-dependent degradation of transcription factors, specificity protein 1 (Sp1), Sp3, and Sp4." (PMID 19396022, 2009). "Thus, targeting the AR/SP1 translational complex showing therapeutic potential in prostate cancer." (PMID 36744249, 2023). "Some evidences in prostate cancer have demonstrated that androgens may downregulate TGFBR2 gene expression through a transcriptional mechanism in which DHT suppresses the binding of the transcription factor Sp1 to the TGFBR2 promoter." (PMID 26091707, 2016). "In addition, motif analyses on accessible chromatin regions by FAIRE-seq identified motifs for a large range of other transcription factors previously linked to prostate cancer development and progression, including CTCF, SP1, FOS, and ETS domain family of transcription factors." (PMID 26412853, 2015). "In summary, our data indicate that the Sp1/Sp3/FLIP signature in combination with Gleason grade is predictive of recurrence of prostate cancer and that its clinical application might avoid unnecessary aggressive interventions, thus improving quality of life and reducing healthcare related expenses." (PMID 23028678, 2012). "It was reported that the downregulation of hTERT was attributed to the suppression of transcriptional factors c-Myc, SP1, STAT3, and protein kinase B/Akt in prostate cancer cells and to both epigenic and genetic regulations in Panc-1 cells." (PMID 40281695, 2025). "As for Sp1, EGCG suppresses the expression, DNA binding activity, and transactivation activity of Sp1 protein in LNCaP prostate cancer cells." (PMID 36677584, 2023). "As a tumor-suppressing factor, MIR361-5p inhibits SP1 and its downstream target PKM2 to impair autophagy and cancer progression of prostate cancer cells." (PMID 35317831, 2022). "In prostate cancer, GPC5 is downregulated, and its upregulation significantly inhibits cancer cell growth and cell invasion by targeting Sp1 through EMT inhibition and Wnt/β-catenin signaling activation." (PMID 35183057, 2022). "In prostate cancer, for example, HDAC3 interacts with the SP1 site on the miR-451 promoter, increasing the miR-451 promoter histone deacetylation to inhibit miR-451 expression." (PMID 33718133, 2021). "In prostate cancer cells, indeed, the direct interaction between VDR and specificity protein 1 (sp1) which, in turn, modulates p27 transcription, seems to be the common mechanism modulating expression of genes without VDR responsive elements." (PMID 32560347, 2020). "It has been reported that quercetin can inhibit the expression and activity of androgen receptor (AR) through Sp1-mediated blockage of c-Jun N-terminal kinase (JNK) signaling pathway, therefore reducing the invasiveness of prostate cancer cells." (PMID 28264020, 2017). "Sp1 was identified as a cardinal transactivator of the IGF1R gene in different tumor types, including prostate cancer." (PMID 27285981, 2016). "In prostate cancer miR-330-3p acts as a tumour suppressor by repressing the translation of E2F1 and Sp1." (PMID 26221725, 2015). "These represented cell cycle/mitosis; among others CCNE1, CCNE2, CCNG2, CCNL1, CCNT1, CDK12 and CDKN3, prostate cancer; including the androgen receptor (AR), metabolism as well as targets of the transcription factors E2F, AP2, SP1, ETF and Pax3." (PMID 26698305, 2015).
prostate carcinoma (continued). "The transcription factors AR and Sp1 were shown to form a nuclear complex and both bound the VEGF core promoter in chromatin of hormone treated CWR22Rv1 prostate cancer cells." (PMID 23369005, 2013). "In experiments to understand the role of FLIP regulation during prostate carcinogenesis, we identified transcription factors Sp1 and Sp3 as important regulators of FLIP transcriptional activity in prostate cancer cells." (PMID 23028678, 2012). "CDDO-Me also inhibited hTERT regulatory proteins such as c-Myc, Sp1, NF-κB, p-STAT-3 and p-Akt in prostate cancer cell lines." (PMID 23519253, 2012). "Recently, transcription factors Sp1, Sp3 and Egr-1 have been identified as potent regulators of MT1-MMP expression in prostate cancer, endothelial and glomerular mesangial cells." (PMID 21176152, 2010). "Evolutionary conserved transcription factor binding sites (TFBS) recognized by WT1, EGR1, SP1, SP2, AP2 and GATA1 were identified in the promoters of 24 differentially expressed prostate cancer genes from eight mammalian species." (PMID 18631392, 2008). "Our results suggest that by inhibiting AR binding to SP1, TQB3720 is effective in prostate cancer." (PMID 36744249, 2023). "Although the transcription factors of stemness genes have similar expressions, they have different contributions between normal and prostate cancer tissues; and particular transcription factors enhance the stemness of prostate cancer, such as PUM1, CLOCK, SP1, TCF12, and so on." (PMID 33985534, 2021). "In the presence of androgens, the most enriched motif corresponded not to ELK1 but to SP1, an AR-interacting protein upregulated in prostate cancer." (PMID 33513133, 2021). "Mechanistically, it appears that androgen induction of VEGF is regulated through AR complex formation with Sp1 in the core promoter region in prostate cancer cells and not via ARE binding sites in the distal VEGF promoter." (PMID 28394264, 2017). "Although androgen can mediate the upregulation of VEGF expression in androgen-dependent prostate cancer cells through the Sp1/Sp3 binding site in the VEGF core promoter, it was not previously known how PPARγ exactly up-regulated VEGF in prostate cancer cells." (PMID 26814431, 2016). "For example, SP1 shows increased phosphorylation under conditions of PI3K/Akt activation, resulting in transcriptional activation of VEGF expression in glioblastoma and prostate carcinoma cells." (PMID 26882471, 2016). "c-Myc, a known myeloma oncogenic TF, has been already shown to transcriptionally repress miR-23a and miR-23b in human prostate cancer cells;27 conversely, regulation of miR-23b by Sp1 has not been previously reported." (PMID 26771806, 2016). "The same assays have been performed also in prostate cancer cells where SP1 depletion did not affect the levels of the target genes." (PMID 26336820, 2015). "Our data suggest that FLIP expression could be positively regulated by Sp1 in tumor cells and that targeting Sp1/Sp3/FLIP could be a potential avenue for clinical management of recurring prostate cancer." (PMID 23028678, 2012). "The observation that Sp1/Sp3 and FLIP may be predictors of clinical outcome could reflect their important role in prostate cancer." (PMID 23028678, 2012). "Further gene silencing experiments using prostate cancer cell lines suggest that Sp1 physiologically regulate FLIP (data not shown)." (PMID 23028678, 2012). "We have identified SP1 as a transcription factor bound to AGAP2 promoter and required for AGAP2 expression in two different types of cancer cells (KU812, a chronic myeloid leukaemia cell line; and DU145, a prostate cancer cell line): silencing SP1 decreased AGAP2 protein levels." (PMID 30674964, 2019). "In addition, the seven articles supporting the connection between ERG and SP1 are from 2007 and earlier, suggesting that the previous studies of Ewing’s sarcoma and acute myeloid leukaemia, and not prostate cancer, may have been overlooked." (PMID 29342271, 2018).
prostate carcinoma (continued). "But whereas mithramycin A and ellipticine target proteins SP1 and TOPIIB are responsible for latent genome replication in hematopoietic cells, knockdown of these proteins in prostate cancer cells did not mimic mithramycin A or ellipticine induced phenotypes." (PMID 40493023, 2025).
pancreatic cancer (88 papers, 2009 to 2026). "Preliminary work has shown that NFATc2 interacts with other transcriptional partners, such as the oncogenic protein Sp1 in pancreatic cancer, and that carcinogenic effects are caused by the interaction of NFATc2 and Sp1." (PMID 36777697, 2022). "In contrast, transcriptional activation of DICER through ERK/Sp1 activation causes pancreatic cancer progression and resistance to gemcitabine." (PMID 34199293, 2021). "We and others have shown that Minnelide decreases oncogenic signaling by downregulating Sp1 and NF-kB in pancreatic tumors and causes regression." (PMID 28801636, 2017). "Since both FXR and Sp1 were associated with the malignant phenotypes of pancreatic cancer, further study is required to determine their potential roles to be candidate therapeutic target in the clinics." (PMID 28402278, 2017). "The gene expression studies identified new targets involved in TA's mode of action, while supporting the hypothesis about the association of Sp1 in TA mediated effects in pancreatic cancer." (PMID 28099934, 2017). "In pancreatic cancer, circ_0026,628 competes with SP1 for binding to miR-346, recruiting FUS to enhance SP1 expression at the post-transcriptional level, thereby strengthening the interaction between SP1 and β-catenin and activating the Wnt/β-catenin pathway." (PMID 40290118, 2025). "Laser capture microdissection‐based proteomics of pancreatic intraepithelial neoplasia (PanIN) identifies specificity protein 1 (SP1) as a key driver of tumorigenesis and progression in pancreatic cancer through glycolytic remodeling." (PMID 40832790, 2025). "Downstream targets of the Wnt/β-catenin pathway, such as SRY-box transcription factor 2 (SOX2), transcriptionally activate SP1, thereby elevating the levels of circ_0026,628 and promoting pancreatic cancer development." (PMID 40290118, 2025). "In pancreatic cancer, Sp1 and STAT3 for example, regulate VEGF and beta-FGF (bFGF) gene expression to promote angiogenesis, metastasis, and tumor cell proliferation." (PMID 38464736, 2024). "In pancreatic cancer, PKCiota upregulated sp1, promoted sp1 to bind with the promoter of YAP1 and transactivated YAP1 expression, and finally promoted pancreatic carcinogenesis." (PMID 38247539, 2024). "Previous studies have shown that combining BA and mitramycin A can inhibit the angiogenesis, proliferation and invasion of pancreatic cancer by down-regulating SP1." (PMID 37415745, 2023). "In conclusion, the present study elucidated a key regulatory loop AK4P1/miR-375/SP1 in pancreatic carcinoma." (PMID 36476264, 2023). "For example, overexpression of LMNB1 in pancreatic cancer cells greatly enhances anchorage-independent growth and migration abilities by targeting Sp1 transcription factor (Sp1)." (PMID 35436411, 2022). "A more recent preliminary expression profile analysis carried out by our group showed the NFATc2- and Sp1-dependent regulation of integrin beta-3 in pancreatic cancer cells." (PMID 36777697, 2022). "Inhibition of PKCι alone or in combination with other inhibitors (e.g., specificity protein 1 (Sp1) inhibitor) reduced cell growth and metastasis and induced apoptosis in pancreatic cancer cells." (PMID 36358843, 2022). "SP1 can also interact with Ajuba to form a complex to induce downstream gene transcription, contributing to an unsatisfactory outcome to pancreatic cancer patients." (PMID 34257529, 2021). "The chemoprevention of curcumin (7.5 μM) and tolfenamic acid (50 μM) synergistically stimulated the apoptotic effects in pancreatic cancer cells via the downregulation of survivin and suppression of specificity protein 1 (Sp1)." (PMID 34299604, 2021). "Mechanically, a novel sp1/p38/ZEB1 regulatory network was found to be involved in ROCK2-mediated gemcitabine resistance in pancreatic cancer cells." (PMID 31783584, 2019).
pancreatic cancer (continued). "Recent investigations have shown the important role of the oncogenic transcription factor Sp1 in the transcriptional activity of NFATc2 in pancreatic cancer, in which interaction between binding partners occurs within the cell." (PMID 30696421, 2019). "The current study also showed the interaction between the transcription factor NFATc2 and the N-terminal domain of Sp1 in pancreatic cancer cells." (PMID 30696421, 2019). "Recent research has shown the importance of the transcription factor Sp1 in the transcriptional activity of NFATc2 in pancreatic cancer." (PMID 30696421, 2019). "The current study shows the interaction between the transcription factor NFATc2 and the N-terminal domain of Sp1 in pancreatic cancer cells." (PMID 30696421, 2019). "A possible new approach to treating pancreatic cancer is inhibiting the interaction between NFATc2 and Sp1." (PMID 30696421, 2019). "In pancreatic cancer, the oncogenic transcription factor Sp1 (specificity protein 1) plays a central role in the transcriptional and functional activity of NFATc2." (PMID 30696421, 2019). "We observed high expression of Sp1, Sp3 and Sp4 in pancreatic tumors from these mice, whereas low expression of these proteins has been reported in normal mouse tissues." (PMID 29389953, 2018). "The role of Sp1 as an essential transcription factor for many genes regulating cell growth, angiogenesis and survival has been proved in pancreatic cancer." (PMID 28192510, 2017). "We have shown previously in pancreatic cancer, that Sp1 is responsible for the transcription of heat shock factor 1 and heat shock protein 70, both of which are known to have a protective role in cancer cells." (PMID 28192510, 2017). "Our studies showed that BAY87-2243 decreased viability of pancreatic cancer cell lines and also decreased the activity of Sp1 and NF-kB the two key oncogenic pathways." (PMID 28801636, 2017). "Further, treatment with triptolide resulted in a decreased activity of Sp1 and NF-kB the two major oncogenic signaling pathway in pancreatic cancer along with a decreased tumor initiating cell (TIC) population in pancreatic tumor." (PMID 28801636, 2017). "We have previously shown that Sp1 downregulation with mithramycin (MTH) results in pancreatic cancer cell death." (PMID 28484232, 2017). "Our previous studies have shown that TA targets the degradation of the Sp1 transcription factor in pancreatic cancer cells." (PMID 28099934, 2017). "Considering the biological significance, we preliminary investigated the machinery whereby FXR interacts with Sp1 in pancreatic cancer." (PMID 28402278, 2017). "Minnelide, a drug that has successfully completed Phase 1 trial and is awaiting Phase 2 trial has shown remarkable effect in downregulating a number of key pancreatic cancer pathways like Sp1 and NF-kB mediated signaling." (PMID 28801636, 2017). "Our study shows that downregulating specificity protein 1 (Sp1), a transcription factor that is overexpressed in pancreatic cancer, activates UPR and results in chronic ER stress." (PMID 28484232, 2017). "As Sp1 was a transcription factor, there was possibility that elevated FXR in pancreatic cancer resultant from elevated Sp1 transcription activity." (PMID 28402278, 2017). "In this study, we show that Sp1 downregulation in pancreatic cancer results in chronic ER stress, which in turn leads to a sustained increase in cytosolic calcium, LMP, and cell death." (PMID 28484232, 2017). "Sp1 has also been identified as a mediator of TGF ß-induced tumor progression in pancreatic carcinoma." (PMID 28774282, 2017). "The oncogenic transcription factor Sp1 plays an important role in the transcriptional and functional activity of NFATc2 in pancreatic carcinoma, in which the binding partners interact in the cell." (PMID 28774282, 2017). "The oncogenic transcription partner Sp1 is important for the transcriptional and functional activity of NFATc2 in pancreatic carcinoma." (PMID 28774282, 2017).